ENSG00000260371 (novel protein)
Gene: Protein-coding gene on chromosome 16 (69,335,091 to 69,356,306, reverse strand). Ensembl gene ENSG00000260371.
Genetic constraint (gnomAD): Loss-of-function variants: 13 observed, 14.21 expected, observed/expected ratio (o/e) 0.91, 90% interval 0.59 to 1.45. Missense variants: 191 observed, 216.38 expected, observed/expected ratio (o/e) 0.88, 90% interval 0.78 to 1. Synonymous variants: 84 observed, 82.14 expected, observed/expected ratio (o/e) 1.02, 90% interval 0.86 to 1.23.